BPTF (bromodomain PHD finger transcription factor)
Diseases named in the same sentence as BPTF in open-access papers (continued):
Sharing a sentence is not in itself a finding about the gene and the disease.
tumor (45 papers, 2009 to 2026). "Given that previous studies demonstrated a positive correlation of BPTF mutation rate with NB primary focal tumor volume, bioinformatics analysis was performed to investigate the role of BPTF in NB progression." (PMID 37170211, 2023). "Our previous research found that the somatic mutation of BPTF gene was positively correlated with NB tumor burden by whole gene exome sequencing." (PMID 37170211, 2023). "Tumor cells with BPTF deficiency display increased CD8+ cell infiltration and CD8+ cell cytotoxicity, including the release of perforin, granzyme and IFN-γ and subsequent induction of the JAK/STAT and Fas/TRAIL pathways." (PMID 34736517, 2021). "The expression levels of circ_BPTF have been found to be increased in BCa tissues and cell lines compared with noncancerous tissues and cell lines, and high levels of circ_BPTF are positively associated with tumour grade." (PMID 33397425, 2021). "BPTF expression has been shown to be increased in several cancer types and was associated with tumor progression and worse survival." (PMID 31769422, 2019). "In hepatocellular carcinoma patients, BPTF was associated with low E-cadherin levels, high tumor numbers, and more vascular invasion." (PMID 30558204, 2018). "After the 2nd and 4 th chemotherapy, the tumor volume reduced and the BPTF gene mutation rate decreased accordingly." (PMID 29467591, 2018). "Correlation analysis showed that the BPTF gene mutation rate was in positive correlation with tumor volume during chemotherapy (CC = 0.428, P = 0.021)." (PMID 29467591, 2018). "In the present study, circ-BPTF was found to be significantly overexpressed in BCa, and this circRNA was closely associated with poor prognosis, tumor grade and recurrence in BCa patients." (PMID 30103209, 2018). "In addition, there was a significant association between BPTF copy number and tumor grade, both as assessed by mean copy number (P<0.05, Fisher exact test) and by percentage of cells with at least 3 copies of BPTF (P<0.02, Chi-square test)." (PMID 36530982, 2022). "Our study showed that BPTF along with other mutations may function as a biomarker for evaluating to effects of chemotherapy to this refractory tumor, and patients with BPTF mutation might have a worse prognosis." (PMID 29467591, 2018). "The mutation rates variation was positively correlated to tumor size (CC = 0.428, P = 0.021), and patients with BPTF mutation may have a worse prognosis compared with wild type." (PMID 29467591, 2018). "Although BPTF is known for its extensive role in regulating immunity in tumor microenvironments, the extent to which AU1 inhibition affects the BPTF immune function remains to be elucidated." (PMID 41278204, 2025). "In this study, we developed a BPTF-targeting PROTAC that not only effectively enhances the effector function of NK cells against primary HCC cells isolated from tumor tissues of HCC patients but also inhibits HCC outgrowth in vivo." (PMID 39935175, 2025). "Our proteomics analysis and immunoblotting results revealed significantly higher BPTF expression in tumor tissues compared with adjacent normal tissues." (PMID 39935175, 2025). "Combined with the existing reports, our study further enriched the anti-tumor function of BPTF, especially its indispensable role in the anti-tumor angiogenesis function mediated by lumbrokinase." (PMID 39062456, 2024). "In Velasco’s research, a BPTF-inhibited mouse model was generated to examine the effect of BPTF on tumor cell proliferation, sensitivity to gemcitabine, and expression of ABC-transporters." (PMID 37450923, 2024). "In #4918 models (high BPTF expression), the gross tumor weight was significantly lower in the erlotinib plus AU‐1 treatment group than that in the vehicle‐, erlotinib‐, or AU‐1 treatment groups." (PMID 37863665, 2023).
tumor (continued). "In the Ruijin cohort (161 pairs of GC tissues and corresponding normal samples), tissue microarray immunohistochemical analysis illustrated that the protein expression of BPTF was high in tumor samples but was extremely low in adjacent non‐tumor tissues." (PMID 37863665, 2023). "Several studies display that BPTF exerts positive impacts on tumor through the MYC pathway, which is a promising signal for further monitoring." (PMID 37794386, 2023). "BPTF copy number gains have been detected in several tumour types, such as lung, prostate, and neuroblastoma." (PMID 35326669, 2022). "In all models used, BPTF-silencing either by CRISPRi or shRNA reduced cell proliferation and tumour growth either in vitro or in vivo, supporting the results obtained in the Ela1-Myc mouse model." (PMID 35326669, 2022). "To validate this synergistic effect in vivo, we subcutaneously implanted in nude mice T3M4 BPTF-silenced and CRISPRi control cells and allowed the tumour to grow to 200 mm3." (PMID 35326669, 2022). "BPTF suppression significantly suppressed (by 57%) the in vivo tumor growth of 231 cells in the mammary fat pad." (PMID 36530982, 2022). "Taken together, we can conclude that BPTF-silencing reduced cell proliferation and migration in vitro, as well as tumour growth in vivo." (PMID 35326669, 2022). "Several studies found that BPTF is required for c-MYC transcriptional activity and is associated with EMT as well as tumor progression." (PMID 35646694, 2022). "In recent years, the role of BPTF in tumor has caught the attention of a large number of researchers." (PMID 36505780, 2022). "After 14 days of tumor growth to 5 × 5 cm, the animals were divided into two groups: one group was injected with control BPTF plasmid and the other group was injected with BPTF shRNA plasmid, once every 4 days for a total of 28 days." (PMID 36529788, 2022). "With these results, we can conclude that BPTF is required for cell proliferation and tumour growth in human PDA." (PMID 35326669, 2022). "Consistent with our results using KPC-derived cells, we observed a dramatic reduction in tumour growth after BPTF-silencing in both human cell lines, along with reduced staining for the proliferative marker Ki67." (PMID 35326669, 2022). "Orthotopic studies further validated the potent role played by BPTF in promoting tumor growth, as evidenced by decreased growth of 231 cells in the mammary fat pad following stable shRNA-mediated BPTF silencing." (PMID 36530982, 2022). "We observed a reduction in tumour growth after BPTF-silencing that was dramatically augmented with gemcitabine treatment, indicating that BPTF-silencing indeed sensitizes tumour cells to gemcitabine." (PMID 35326669, 2022). "To demonstrate that BPTF is required for cells’ proliferation in human PDA tumours, we downregulated BPTF levels using CRISPRi." (PMID 35326669, 2022). "KEGG pathway analysis indicated that the BPTF signature was mainly enriched in tumor-related pathways, of which the top hit was the glycolysis pathway." (PMID 33664855, 2021). "BPTF, which is highly expressed in NSCLC tumor tissues, is positively associated with advanced clinical stage, more lymph nodes and distant metastasis." (PMID 34736517, 2021). "Mutations of BPTF, encoding a bromodomain PHD-finger transcription factor, was identified in primary tumor and CTCs." (PMID 34616428, 2021). "Knockdown of BPTF impairs tumor development with inactivation of the c-MYC and/or c-Myc target genes transcriptional program in preneoplastic pancreatic acinar cells and high-grade glioma." (PMID 34736517, 2021). "Further study of the molecular mechanisms showed that BPTF promotes tumor cell proliferation, tumor metastasis and stemness maintenance by activating hTERT expression in HCCs." (PMID 33117795, 2020). "Consistently, BCa patients with higher expression levels of circ-BPTF were found to have higher tumor grades and poorer prognosis." (PMID 30103209, 2018).
tumor (continued). "To discover novel roles for BPTF in tumor biology, we transplanted the 66cl4 or 67NR lines into the 4th mammary fat pad of syngeneic BALB/c mice." (PMID 28969075, 2017). "Blocking mouse NCR1 in vivo rescues BPTF KD tumor weights, demonstrating its importance for the control of tumor growth." (PMID 28969075, 2017). "These experiments showed equivalent BPTF KD tumor weights to controls, demonstrating the immune system is required to reduce the growth of BPTF KD tumors." (PMID 28969075, 2017). "BPTF KD in established tumors significantly reduced tumor weights compared to controls, and we occasionally observed complete 66cl4 tumor regression with BPTF KD (rAd BPTF shRNA = 3 of 17 treated tumors, rAd control shRNA = 0 of 16 treated tumors)." (PMID 28969075, 2017). "Using transplantable tumor models, we tested this prediction and discovered that BPTF, and by extension NURF, represses NK-mediated antitumor activity." (PMID 28969075, 2017). "BPTF depletion in 66cl4 tumors with rAd resulted in tumor regression with about 18% frequency, despite incomplete BPTF KD." (PMID 28969075, 2017). "We next examined the abundance and activation of NK cells in the BPTF KD tumor microenvironment (TME)." (PMID 28969075, 2017). "We next used the NCR1 blocking mAb in tumor bearing mice and observed that BPTF KD tumor weights are rescued with NCR1 blocking." (PMID 28969075, 2017). "To identify immune cells that are important for reducing BPTF KD tumor growth, we repeated our tumor studies in mice depleted of NK cells, CD8+ T cells, or CD4+ T cells by monoclonal antibody (mAb) treatments." (PMID 28969075, 2017). "To confirm the importance of the immune response for BPTF KD tumor growth, we repeated our tumor studies in an immune-deficient NOD/SCID, Ifrg2r−/− (NSG) background." (PMID 28969075, 2017). "Consistent with this, BPTF expression in human tumours positively correlates with activation of c-MYC gene signatures." (PMID 26729287, 2016). "Compared to the control shRNA treated group, the tumor volume and weight were significantly reduced in the group treated with the BPTF shRNA." (PMID 26418899, 2015). "Next, we also examined the effect of BPTF shRNA on the expression of some key proteins in the tumor tissues by Western blot." (PMID 26418899, 2015). "Among 75 patients’ tumor tissue samples tested, about 53 (70.7%) patients showed high expression of BPTF." (PMID 26418899, 2015). "Afterward, we proceeded to validate whether the degradation of BPTF by PROTAC 8d could enhance the susceptibility of primary HCC cells, isolated from HCC patients’ tumor tissues, to NK cell-mediated cytotoxicity." (PMID 39935175, 2025). "This suggests that highly selective inhibitors targeting BPTF could potentially enhance the efficacy of NK cell-based anti-tumor responses." (PMID 39935175, 2025). "Furthermore, the results of quantitative RT‐PCR (qRT‐PCR) illustrated that the mRNA expression level of BPTF was elevated in tumor tissues in contrast to corresponding non‐tumor samples (n = 28 patients with GC)." (PMID 37863665, 2023). "Among them, the relationship between BPTF and tumor development has been gradually revealed." (PMID 37170211, 2023). "Our findings provided new clues that hsa_circRNA_102051 might be a potential predictive or prognostic factor in CRC, which induced the fluctuation of downstream miR-203a/BPTF, and subsequently influenced tumor growth, activities and stemness." (PMID 37794386, 2023). "Furthermore, BPTF was found to be overexpressed in tumor samples compared to corresponding adjacent tissues." (PMID 37794386, 2023). "Furthermore, in the TCGA‐STAD cohort, the PLCG1 expression level was elevated in tumor tissues in contrast to adjacent non‐tumor tissues and was highly correlated with BPTF expression." (PMID 37863665, 2023). "It is important to note that bromosporine targets different bromodomains and its anti-tumor activity may extend beyond BPTF targeting alone." (PMID 36530982, 2022).
tumor (continued). "We observed that BPTF downregulation strongly reduces tumour progression in vivo." (PMID 35326669, 2022). "We analyzed BPTF copy number in a tissue microarray cohort and identified copy number gains in 34.1% of cases, which significantly correlated with increasing patient age and tumor grade." (PMID 36530982, 2022). "Thus, all these experiments clearly demonstrate for the first time that BPTF-silencing synergizes with gemcitabine in vitro and in vivo, leading to a strong tumour response." (PMID 35326669, 2022). "Circ-BPTF also plays an important role in tumor progression." (PMID 34736517, 2021). "In accordance with our speculations, BPTF was highly expressed in tumor samples, especially in metastatic cases, with P < 0.001." (PMID 33664855, 2021). "Furthermore, we constructed an in vivo metastatic model and observed that BPTF knockdown significantly suppressed the tumor metastatic ability of METTL14-/- cells, which were quantified and compared by the number or size of lung metastatic lesions." (PMID 33664855, 2021). "One study reported that BPTF could activate oncogenic signaling and synergize with other proteins to regulate tumor progression." (PMID 33117795, 2020). "In addition, down-regulation of BPTF expression affected cell colony formation, proliferation, chemotherapy resistance and apoptosis and tumor progression in HCC." (PMID 33117795, 2020). "Functionally, knockdown of circ-BPTF inhibited tumor progression in vitro and in vivo." (PMID 30103209, 2018). "BPTF and TMCO3 mutations were detected at the time of diagnosis, after chemotherapy, BPTF mutation rate decreased, together with C20orf96 and LOC100996470, indicating tumor burden reduced, and BPTF may contribute to bone marrow metastasis." (PMID 29467591, 2018). "Additionally, we found that overexpression of circ-BPTF correlated with poor survival, high tumor stage and tumor recurrence, suggesting that circ-BPTF exerts an oncogenic effect in BCa." (PMID 30103209, 2018). "Because RAB27A is known for its strong tumor-promoting effect in BCa progression, we hypothesized that the oncogenic effect that circ-BPTF exerts in BCa can be partially attributed to a circ-BPTF/miR-31-5p/RAB27A axis." (PMID 30103209, 2018). "Also consistent, we observe rescue of BPTF KD tumor growth when NCR1 blocking mAb are used in vivo and is consistent with other reports that NCR1 is important for antitumor activity." (PMID 28969075, 2017). "In these tumours, BPTF expression levels also correlated positively with c-MYC signatures." (PMID 26729287, 2016). "BPTF is overexpressed in tumours together with c-MYC and, in some cases, N-MYC and L-MYC." (PMID 26729287, 2016). "Similarly, BPTF knockdown in PK9 and MIA Paca-2 cells led to reduced proliferation, indicating that tumour types with different c-MYC dependency require BPTF to sustain proliferation." (PMID 26729287, 2016). "Especially, we proved BPTF has marked effect on tumor growth in vivo." (PMID 26418899, 2015). "Similarly, BPTF expression in primary PCa tissues is comparable to that in most other tumor types." (PMID 41381516, 2025). "The identification of transcription factors such as BPTF, SOX4, and KLF5 in ITGB8-high cells further implicates these factors in regulating tumor–stroma interactions and mediating the aggressive phenotype associated with a high MTSR." (PMID 41602481, 2026). "The bromodomain PHD finger transcription factor (BPTF), a core subunit of nucleosome-remodeling factor (NURF) complex, serves as a transcriptional regulator which facilitates tumor progression." (PMID 39077467, 2024). "Lumbrokinase down-regulated the expression of BPTF and reduced the binding of BPTF at the VEGF promoter region, which in turn inhibited the transcription of VEGF and ultimately restrained tumor vascular prosperity and sensitized NSCLC to bevacizumab treatment." (PMID 39062456, 2024).
tumor (continued). "BPTF promotes CRC cell cycle progression, thus CRC proliferation and overall tumour progression by targeting Cell division cycle 25 A (Cdc25A)." (PMID 38067326, 2023). "In the ESCC study, a novel NSUN2 methylated lncRNA NMR regulated tumor metastasis and drug resistance via NSUN2 and BPTF." (PMID 37275549, 2023). "Tumor growth rate was higher in MGC803/BPTF‐NC and HGC27/BPTF‐OE cells but was significantly lower in MGC803/BPTF‐KO and HGC27/BPTF‐NC cells." (PMID 37863665, 2023). "High BPTF can promote the chromatin accessibility within the promoter region of ENO2 and SRC, improving the glycolytic activity of tumor cells." (PMID 36967443, 2023). "We demonstrated that BPTF-silencing reduced the expression of several ABC-transporters, which are involved in gemcitabine resistance, and enhanced its accumulation in the tumour cell, improving its therapeutic effect." (PMID 35326669, 2022). "Immunohistochemical detection showed that BPTF and VEGF were relatively highly expressed in tumor tissues of patients with bevacizumab treatment sensitivity group." (PMID 36529788, 2022). "BPTF-silencing impairs cell proliferation and migration in PDA tumours, and strongly enhances the sensitivity to gemcitabine through the downregulation of ABC-transporters in a c-MYC-dependent manner." (PMID 35326669, 2022). "Our previous work showed the therapeutic potential of BPTF in a PDA mouse model driven by c-MYC (Ela1-c-MYC), reducing cell proliferation and tumour growth." (PMID 35326669, 2022). "To analyze if BPTF levels correlate with tumour proliferation, we assessed BPTF expression in a panel of 11 human PDA cell lines and selected four cell lines representative of the varying BPTF levels observed." (PMID 35326669, 2022). "To overcome this issue, in this study, we aim to validate the therapeutic value of BPTF by itself and in combination with gemcitabine in PDA KRAS-driven tumours either in vitro or in vivo using preclinical immunodeficient and immunocompetent mouse models." (PMID 35326669, 2022). "BPTF expression was present in the nucleus of PTC cells and normal thyroid follicle epithelial cells adjacent to the tumor." (PMID 35646694, 2022). "Mechanistically, BPTF is required for c-MYC recruitment to the promoter of ABC-transporters and its downregulation facilitates gemcitabine accumulation in tumour cells, increases DNA damage, and a generates a strong synergistic effect in vivo." (PMID 35326669, 2022). "Tumors were removed, and the expression of BPTF and VEGF in tumor tissues of mice was detected by immunofluorescence method." (PMID 36529788, 2022). "The bromodomain PHD finger transcription factor (BPTF), constituting the largest subunit of the NURF complex, was reported to participate in tumor progression mainly by regulating DNA accessibility and gene expression." (PMID 33664855, 2021). "We predict that BPTF, SIN3A and CNOT1 enhance genomic stability and inhibit tumor cell formation by positively regulating ubiquitination in ccRCC." (PMID 33232269, 2020). "We also found BPTF was highly expressed in NSCLC cell lines and tumor tissues compared to the normal cell or adjacent tissues." (PMID 26418899, 2015). "Moreover, lumbrokinase was found to inhibit tumor angiogenesis and sensitize NSCLC cells to bevacizumab via the targeted down-regulation of BPTF, weakening the binding of BPTF to the VEGF promoter, thereby decreasing the expression of VEGF." (PMID 39062456, 2024). "BPTF targeting with the bromodomain inhibitor bromosporine, alone or in combination with the PI3K pathway inhibitor gedatolisib, produced significant anti-tumor effects against TNBC cells in vitro and in vivo." (PMID 36530982, 2022). "We anticipate that a panel of markers, such as BPTF, TMCO3, CUX2, combined with classic markers: PHOX2B, TH, DCX, will prove valuable in a variety of clinical settings, including the assessment of tumor, drug resistance, residual disease monitoring and prediction of recurrence." (PMID 29467591, 2018).